MTOR (mechanistic target of rapamycin kinase)
Diseases named in the same sentence as MTOR in open-access papers (continued):
Sharing a sentence is not in itself a finding about the gene and the disease.
cancer (continued). "The AKT/mTOR axis is a classic signaling pathway in cancers that blocks catabolic activities, such as autophagy." (PMID 36976201, 2023). "Investigations into the mechanisms by which mTOR regulates necroptosis have shed more light on potential therapeutic targets for an extensive array of diseases, including immune-related diseases, cancer, drug toxicity, and more." (PMID 38164133, 2023). "Both selenium‐rich foods (containing organic and inorganic Se) and Se nanoparticles significantly inhibited the activation of PI3K/AKT/mTOR signaling pathway in cancers." (PMID 37606338, 2023). "In cancer cells, mTOR is most important for protein synthesis via phosphorylating the essential molecules that regulate mRNA translation, and ribosome synthesis." (PMID 36737760, 2023). "In normal cells, mTOR regulates cell growth and division, but in cancer cells, mTOR signals tumor growth, metastasis and invasion of healthy tissues." (PMID 37180606, 2023). "Conversely, activation of mTOR signaling has been reported to drive changes in cancer cell metabolism by promoting several metabolic pathways such as glucose, amino acid, nucleotide, fatty acid, and lipid metabolism." (PMID 37259304, 2023). "The situation in cancer therapy targeting mTOR is very complicated because the signal pathways always influence each other and coordinate with each other." (PMID 37049920, 2023). "It is commonly believed that metformin exerts its anti-cancer activity via the LKB1–AMPK–mTOR pathway, and the overexpression of mTOR in this pathway is often associated with the development of numerous diseases such as tumors, among others." (PMID 36830619, 2023). "PI3K inhibitors are an exciting target for cancer therapy because upregulation of the PI3K/AKT/mTOR pathway is present in almost all cancers." (PMID 38983593, 2023). "As a downstream effector of the PI3K/Akt pathway, mTOR plays a major role in regulating protein synthesis and degradation in cancer cells." (PMID 37958470, 2023). "Its efficacious multikinase properties make it an advantageous approach to cancer therapy compared to kinase inhibitors like TP-3654 or dual PI3K/mTOR inhibitors." (PMID 37943821, 2023). "Similar to AMPK, the hyperactivation of the PI3K/AKT/mTOR signaling pathway promotes cancer proliferation, growth, invasion, and metastasis." (PMID 37384249, 2023). "The over-activated PI3K/Akt/mTOR pathway leads to the manifestation of a variety of cancer hallmarks, including growth signal autonomy, evasion of apoptosis, induction of angiogenesis, tissue invasion and metastasis, and insensitivity to antigrowth signals." (PMID 37047624, 2023). "Overexpression of glucose transporter 1 (GLUT1), activation of AMP-activated protein kinase (AMPK), and downregulation of mammalian target of rapamycin (mTOR) have been identified as biomarkers of abnormal cancer cell metabolism." (PMID 36850263, 2023). "The PI3K/Akt/mTOR pathway plays a crucial role in various hallmarks of cancer; these include sustaining proliferative signaling, evading growth suppressors, activating invasion and metastasis, and deregulating cellular energetics." (PMID 37958470, 2023). "Later, because the mTOR signaling pathway is active in most human cancers, the first- and second-generation mTOR inhibitors for cancer treatment were developed." (PMID 37097377, 2023). "In fact, conversion of tacrolimus to sirolimus has been shown previously by our group to result in decreased pro‐cancer gene expression, including genes such as eIF2 as well as genes along the mTOR pathway which become downregulated." (PMID 36205189, 2023). "Many signaling pathways, such as PI3K/AKT/mTOR, Wnt/β-catenin and NF-κB, have been described to promote cell survival, proliferation and tumorigenesis in cancer cells." (PMID 36282364, 2023). "The interconnection between the Wnt/β-catenin and PI3K/AKT/mTOR pathways has been widely demonstrated in distinct cancer settings." (PMID 37490168, 2023).
cancer (continued). "Dysregulation of the mTOR kinase pathway is an essential factor in the pathogenesis of various human diseases, especially cancer, where it controls cell metabolism by altering key metabolic enzymes’ expression and/or activity." (PMID 37446128, 2023). "Accumulating data established the mammalian target of rapamycin (mTOR) as an important effector in metabolic pathways generally dysregulated in human cancers." (PMID 36816923, 2023). "In cancer prone mice, mTOR inhibition by rapamycin was able to increase the lifespan, which is partially accomplished by the delay of tumor development in multiple tissue types through the treatment." (PMID 37904250, 2023). "For this reason, either targeting cancer cells by synthetic or natural products affecting the Akt/mTOR pathway down-regulation is a useful strategy in cancer therapy." (PMID 36721812, 2023). "Oncogenic activation of phosphatidylinositol-3-kinase (PI3K), AK strain transforming (AKT), and mechanistic/mammalian target of rapamycin (mTOR) pathways are the most frequently activated in cancers, including AML patients." (PMID 38435444, 2023). "Overexpression of PI3K/AKT/mTOR signaling has been reported in diverse forms of cancer, particularly CRC." (PMID 36768278, 2023). "The phosphoinositide 3-kinase (PI3K)/protein kinase B (Akt)/mammalian target of rapamycin (mTOR) (PI3K/Akt/mTOR) is one such pathway, whose deregulation has been found to be associated with various types of human cancers." (PMID 37047624, 2023). "To investigate the roles of the PI3K/AKT/mTOR pathway in cancer cells when exposed to a high-POSTN environment, we cultured HEYA8 cells in 3D with either CMPOSTNhigh or CMCTL medium, CMCTL + MK2206 (AKT inhibitor), or CMPOSTNhigh + MK2206 for 72 h." (PMID 38049490, 2023). "Some natural inducers promote ferroptosis by regulating the ROS/AMPK/mTOR signaling pathways to inhibit cancer cell viability and proliferation, such as dihydroartemisinin (DHA) and amentoflavone." (PMID 36677534, 2023). "Signaling by mTOR is commonly activated in tumors and controls cancer cell metabolism by altering key metabolic enzymes’ expression and activity." (PMID 36980552, 2023). "In the context of the PI3K pathway, the nutrient-sensing serine/threonine kinase mTOR regulates developmental progression, and promotes tumor growth and metastasis in diverse cancer types." (PMID 37278614, 2023). "PI3K/Akt/mTOR, JAK-STAT, AMPK, and Wnt/β-catenin pathways have been strongly implicated with cancer metabolism." (PMID 37730663, 2023). "The mechanistic target of rapamycin (mTOR) is a dual-specificity protein kinase phosphorylating serine/threonine as well as tyrosine residues, and its role in cancer is known." (PMID 37298670, 2023). "The AMPK/mTOR signaling pathway is closely related to the enhancement of autophagy and is always activated in cancers." (PMID 36770781, 2023). "Flavonoids such as quercetin and pomegranate fruit polyphenols induce regulatory T cells by inhibiting mTOR (mechanistic target of rapamycin), at least in human cancer cells, and reducing inflammatory markers." (PMID 37374069, 2023). "Within the malignant epithelial cells, we observed enrichment for the EMT signature in G1-arrested cancer cells while the PI3K/AKT/mTOR signalling was active in cycling cells (S and G2/M phases)." (PMID 36949044, 2023). "MYC promoted PCa oncogenic signaling via the PI3K/AKT/mTOR pathway, thereby stimulating massive cancer cell growth." (PMID 37730847, 2023). "The PI3K/Akt/mTOR signaling is hyperactivated in many cancers, inducing tumorigenesis and resistance to chemotherapy." (PMID 38135881, 2023). "Various inhibitors of pan-PIK3 and mTOR pathways are individually approved in cancer treatment, and clinical trials for others are underway." (PMID 36244040, 2023).
cancer (continued). "Because mTOR inhibitors and drugs targeting molecules upstream of mTOR, such as PI3K inhibitors, are approved for treatment of cancer, it is essential to elucidate the role of mTOR in T cell exhaustion to further improve immunotherapy for patients with cancer." (PMID 36378537, 2023). "It has been proven that PI3K/AKT/mTOR signaling regulates apoptosis and autophagy and constitute a molecular target for cancer therapy." (PMID 36726491, 2023). "As p70S6K is a downstream effector of mTOR, inactivation of the AKT/mTOR pathway therefore efficiently interferes with the activation of p70S6K, leading to significant reduction in cancer growth in animal models." (PMID 36903477, 2023). "Contribution of the PI3K/AKT/mTOR pathway to chemotherapy resistance has been confirmed in various cancers." (PMID 37937323, 2023). "Our findings revealed that upregulated YB1 protein maintained cellular native autophagy at a high level through regulating the mTOR signaling pathway to enhance cancer cell tolerance for environmental stress." (PMID 37035211, 2023). "Efforts towards inhibiting mTOR with rapalogs (including rapamycin and analogs) have been pursued in cancer therapeutics; however, the exclusive utilization of rapalogs displayed suboptimal efficacy." (PMID 37760640, 2023). "Mechanically, this anti-cancer potentiation is attributed to the induction of autophagy via the Sestrin/AMPK/ULK/mTOR axis." (PMID 36677797, 2023). "The PI3K/Akt/mTOR signaling axis is well known to play a key role in cancer development and progression." (PMID 36969070, 2023). "mTOR, a serine/threonine kinase, contributes to cancer cell growth and survival, while PI3K signaling activation is associated with poor prognostic in cancer patients." (PMID 36673365, 2023). "With the advent of high-throughput sequencing technology, a multitude of tumor genomics investigations have corroborated the aberrant activation of the PI3K/AKT/mTOR signaling pathway in malignant tumors." (PMID 37152048, 2023). "Pathway enrichment analysis of DNAm probes associated with suicidal ideation also identified numerous KEGG terms, including AMPK signaling, insulin signaling, mTOR signaling, and numerous cancers (i.e., gastric, pancreatic, breast, and prostate)." (PMID 37398583, 2023). "A major pathway targeted by therapeutic drugs in human cancers is the PI3K/AKT/mTOR signaling pathway." (PMID 37569713, 2023). "The PI3K/AKT/mTOR axis induced by growth factors is an essential signalling pathway in cancer cell growth in nutrient-rich conditions." (PMID 36994671, 2023). "FASN has been shown to be O-GlcNAcylated, which enhances the enzymatic activity of this fatty acid synthesizing enzyme, further supporting the intensive crosstalk between OGT, FASN, and the mTOR pathway in cancer." (PMID 37838167, 2023). "Although it has been shown that COMP promotes cancer-cell proliferation via activation of the PI3K/Akt/mTOR/p70S6K signaling pathway, more studies are required to decipher the role of this protein in cancer progression and metastasis." (PMID 36765749, 2023). "Considering the implication of the PI3K/AKT/mTOR signaling pathway in most human cancers, the effect of C-VGB3 on this pathway was evaluated in 4T1 MCT cells." (PMID 37375853, 2023). "As a new class of immunosuppressive medication, mTOR has potential antitumorigenic effects by blocking the pathway that is vital for cancer progression." (PMID 37351559, 2023). "PTPRZ1 overexpression on its own would be expected to abrogate AKT/mTOR signaling and cancer progression." (PMID 36966348, 2023). "It has been demonstrated that treatment resistance in a variety of cancer types is correlated with the stimulation of mTOR signaling pathways." (PMID 37895091, 2023). "The mTOR inhibitor everolimus shows an antitumor effect in malignant peripheral nerve sheath tumor-bearing mouse models by promoting a cytostatic effect." (PMID 37173935, 2023).
cancer (continued). "In the past few years, PI3K and AKT have become the research objects of targeted cancer therapy due to their crucial roles in the PI3K/AKT/mTOR signalling cascade." (PMID 37489050, 2023). "Everolimus, an oral mammalian mTOR inhibitor, has antitumor activity in multiple cancer types, and previous research demonstrated that everolimus has some clinical benefit in patients with metastatic PRCC." (PMID 36927438, 2023). "As mTOR plays a crucial role in the development of tumours, mTOR inhibitors have the potential to be effective in various cancer treatments." (PMID 37513916, 2023). "The mammalian target of rapamycin (mTOR) is a potential target in ES because it was highlighted that ES expresses and upregulates, by phosphorylation, this crucial pathway for cancer cell proliferation and survival." (PMID 36979853, 2023). "In this review, we will explore the current developments in the mTOR signalling pathway and its importance for being targeted by various inhibitors in anti-cancer therapeutics." (PMID 37513916, 2023). "The PI3K/mTOR pathway is frequently activated in diverse cancer types, as it necessitates prompt response to extracellular signals." (PMID 37658623, 2023). "The mTOR gene and its signaling pathway are frequently deregulated in human cancer and have become a major therapeutic target." (PMID 36980552, 2023). "Small molecule drugs targeting the Hippo signaling pathways and PI3K/AKT/mTOR have shown promise in clinical trials and offer exciting possibilities for targeted cancer therapy." (PMID 37544991, 2023). "The phosphatidylinositol 3-kinase (PI3K)/protein kinase B (AKT)/mammalian target of rapamycin (mTOR) signaling pathway is the most common activated signaling pathway in cancer including CRC." (PMID 37894822, 2023). "The mTOR pathway regulates a variety of physiological processes, including cell growth and cancer progression." (PMID 37190070, 2023). "For example, HK can induce autophagy in different cancer cells by downregulating the PI3K/Akt/mTOR signaling pathway." (PMID 37212560, 2023). "Concerning high metabolically active cells, mTOR is a particularly relevant signalling pathway in cancer cells." (PMID 36830073, 2023). "Activation of PI3K/AKT/mTOR axis in cancer cells not only suppresses autophagy but also induces protein translation, cell growth, and proliferation to drive tumorigenesis." (PMID 37575061, 2023). "This shows that safranal’s ability to inhibit GBM cells is most likely achieved by inhibiting the PI3K/Akt/mTOR axis, increasing cancer cell apoptosis and regulating the cancer cell cycle." (PMID 37736545, 2023). "These pathways encompass Glycolysis, TGF Beta signaling, PI3K/AKT/MTOR signaling, as well as Interferon Alpha and Interferon Gamma Responses across various cancer types." (PMID 37762224, 2023). "On the other hand, mTOR inhibitors are reported to exert promising effects by restricting cancer by their kinase activity targeting the downstream mTOR kinase molecules of PTEN in KSHV-infected cells." (PMID 37602330, 2023). "At the same time, it can also inhibit tumor invasion, migration, and angiogenesis by regulating miRNA or AMPK/mTOR and other signaling pathways, and induce cancer cell apoptosis and protective autophagy." (PMID 36639776, 2023). "Mammalian TOR (mTOR) dysregulation is believed to play important roles in autoimmunity, cancer, cardiovascular disease, metabolic disorders, and fungal virulence and pathogenicity." (PMID 36909734, 2023). "These include cell proliferation, survival, metabolism, angiogenesis, migration, invasion, and resistance to anti-cancer drugs, and Akt/mTOR activation is common in cancer cells." (PMID 37571343, 2023). "It has been reported that metformin also blocks HIF-1α accumulation through suppression of the mTOR pathway in different types of cancer." (PMID 37760498, 2023).
cancer (continued). "In fact, the results we present here indicated that KR induces the phosphorylation of S6K in 4T1 cancer cells; rapamycin, an mTORC1 inhibitor, attenuates the autophagy induction by KR with the suppression of mTOR/S6K signaling." (PMID 37760498, 2023). "The PI3K/AKT/mTOR pathway is altered in many human cancers, including breast and ovarian cancers, and has been extensively studied as a target for anticancer therapies for many years." (PMID 37644890, 2023). "The phosphatidylinositol (PI3K)/AKT/mTOR axis represents an important therapeutic target to treat human cancers." (PMID 37569713, 2023). "The PI3K/AKT/mTOR signaling pathway regulates crucial cellular processes in the physiological setting as well as most hallmarks of cancer, including cell cycle, survival, metabolism, motility, and angiogenesis." (PMID 36768977, 2023). "It has been shown that strong expression of GABARAPL1 attenuates AKT activation, reduces mTOR activation, and increases cancer cell invasion." (PMID 37240068, 2023). "In summary, CO-RMs inhibit the PI3K/Akt/mTOR pathway, thereby suppressing cancer tumor cell multiplication signaling." (PMID 37895865, 2023). "Currently, there are many clinical trials that evaluate the use of the PI3K and mTOR inhibitors in different cancer types, and some are FDA-approved." (PMID 37109772, 2023). "Thereinto, FC epsilon RI signaling pathway has many connections with immune function, while mTOR signaling pathway and JAK/STAT signaling pathway are closely associated with cancers." (PMID 37352167, 2023). "Overall, these findings indicate a link from mTOR signaling to mammary stem and progenitor cell activity and cancer progression." (PMID 37904250, 2023). "Second, the associations between cancer grade and WNT-1 and mTOR expression are supported by immunohistochemical findings." (PMID 37176048, 2023). "In the era of precision oncology, AKT represents an attractive therapeutic target for the discovery of pathway-based targeted therapies selectively hitting cancer cells characterized by aberrant activation of PI3K/AKTs/mTOR signaling pathway." (PMID 37513905, 2023). "Colchicine also induces caspase-3-mediated apoptosis via suppressing the PI3K/Akt/mTOR signaling pathway in some cancer cell lines." (PMID 37711850, 2023). "Dactolisib suppresses PI3K kinase and mTOR kinase in the PI3K/AKT/mTOR kinase pathway, inducing tumor cell apoptosis and inhibiting growth in PI3K/mTOR highly expressing cancer cells." (PMID 37046703, 2023). "Together, these findings reveal the extensive crosstalk between OGT and mTOR pathway and their role in regulating cancer cell proliferation and tumor growth." (PMID 37838167, 2023). "mTOR is frequently activated in human cancer, and activated mTORC1 phosphorylates and activates downstream effectors p70S6K and the eukaryotic initiation factor 4E (eIF4E) binding protein 1 (4EBP1) to initiate protein translation/synthesis." (PMID 37284309, 2023). "The mTOR pathway has been explored as a potential therapeutic target in cancer as it integrates two of the main signals in the regulation of cell growth activated by tyrosine kinase receptors and nutrients, including amino acids and glucose." (PMID 37223676, 2023). "Recent studies have shown the central role of mTOR complex 2 (mTORC2) as a pro‐tumourigenic factor of the PI3K/AKT/mTOR pathway in a number of cancers." (PMID 37877351, 2023). "Mechanistic target of rapamycin (mTOR) is a protein kinase that regulates a range of processes important in cancer, such as cell proliferation and autophagy, and many inhibitors of mTOR have been developed for cancer treatment." (PMID 37756103, 2023). "The experience of treatment of cancer patients with mTOR inhibitors is also in agreement with their cancer-preventive effects." (PMID 37057884, 2023).